TNF (tumor necrosis factor)
Diseases named in the same sentence as TNF in open-access papers (continued):
Sharing a sentence is not in itself a finding about the gene and the disease.
rheumatoid arthritis (continued). "In the BiOCURA (Biologicals and Outcome Compared and predicted Utrecht region in Rheumatoid Arthritis) cohort of 105 RA patients taking TNF antagonists, combining four metabolites with several clinical parameters correctly classified 60% of patients by responder status." (PMID 34940570, 2021). "In rheumatoid arthritis (RA), synoviocytes express the truncated form of Trx-80, and treatment with the proinflammatory cytokines IL-1β and/or TNF-α increases Trx-80 cell expression, playing an important role in the establishment and/or the development of RA autoimmunity." (PMID 35008500, 2021). "Similarly, a study in Boston at BRASS (Brigham and Women's Hospital Rheumatoid Arthritis Sequential Study) showed that 42% of patients with RA reported abandonment of their anti-TNF therapy due to ineffectiveness." (PMID 34059137, 2021). "Tumor Necrosis Factor (TNF)-α plays a central role in the pathophysiology for many diseases, such as rheumatoid arthritis (RA), juvenile idiopathic arthritis (JIA), inflammatory bowel disease (IBD) and non-infectious uveitis (NIPU)." (PMID 33634341, 2021). "KEGG pathway analysis showed enrichment of chemokine signaling pathway, cytokine–cytokine receptor interaction, rheumatoid arthritis, Toll-like receptor (TLR) signaling pathway, TNF signaling pathway." (PMID 34321012, 2021). "Studies have shown that BF can reduce tumor necrosis factor-α (TNF-α)-induced interleukin-1beta (IL-1β), IL-6 and IL-8 production in rheumatoid arthritis fibroblast-like synoviocytes, suggesting an anti-inflammatory role of BF in these cells." (PMID 35011278, 2021). "Our previous studies using TNF-Tg mice, a mouse model of rheumatoid arthritis (RA), demonstrated that inhibition of lymphangiogenesis via VEGFR-3 blockade increases, while stimulation of lymphangiogenesis via VEGF-C administration decreases the severity of joint inflammation and tissue damage." (PMID 33602317, 2021). "TNF levels are increased in most chronic inflammatory diseases, supporting the involvement of ADAM17 in their progression, including rheumatoid arthritis (RA)." (PMID 33579029, 2021). "Overexpression of master pro-inflammatory cytokine tumor necrosis factor alpha (TNF-α) plays a crucial role in the pathogenesis of autoimmune disorders such as rheumatoid arthritis (RA), psoriasis (PsO), ankylosing spondylitis (AS), ulcerative colitis (UC), and crohn’s disease (CD)." (PMID 34025650, 2021). "However, anti-TNF-α monoclonal antibodies are used routinely to treat rheumatoid arthritis (RA), ankylosing spondylitis (AS) or psoriasis." (PMID 34307414, 2021). "This is an anti-TNF-α monoclonal antibody approved by FDA and EMA for the treatment of rheumatoid arthritis, Crohn’s disease, axial spondyloarthritis, and psoriasis." (PMID 34832866, 2021). "Tumor necrosis factor-α (TNF-α) and interleukin-1β (IL-1β) are two cytokines involved in the perpetuation of the chronic inflammation state characterizing rheumatoid arthritis (RA)." (PMID 34201546, 2021). "Brucine reduces the expression of TNF-α and VEGF to inhibit the abnormal proliferation of FLS, thereby alleviating the symptoms related to rheumatoid arthritis." (PMID 34108880, 2021). "Au(I) compounds reduce TNF-α via the action of certain immune cells, including neutrophils and macrophages, and Au(I) compounds enhance leukocyte adhesion to endothelial cells, both of which are important in the pathogenesis of rheumatoid arthritis (RA)." (PMID 34588987, 2021). "TwHF significantly inhibits inflammatory molecules including IL-6, TNF-α, and COX-2 which are up-regulated in the development and progression of rheumatoid arthritis." (PMID 34108880, 2021). "Also, repeated observations that the treatment of inflammatory diseases such as psoriasis, rheumatoid arthritis, and Crohn's disease with TNF antagonists improves glycemia, provides additional hints that TNF may, indeed, have an important role in metabolic diseases." (PMID 34616762, 2021).
rheumatoid arthritis (continued). "Therapeutics that block tumor necrosis factor (TNF), and thus activation of TNF receptor 1 (TNFR1) and TNFR2, are clinically used to treat inflammatory diseases such as rheumatoid arthritis, inflammatory bowel disease and psoriasis." (PMID 34305946, 2021). "Tumor necrosis factor alpha (TNF-α), which is involved in several pathologies such as septic shock and rheumatoid arthritis, has pleiotropic effects and regulates the expression of several inflammatory genes." (PMID 34539391, 2021). "PTX3 expressed by numerous cell types after stimulation with cytokines (e.g. IL-1β and TNF-α), TLR agonists or microbes in inflammation is found to be increased in rheumatoid arthritis synovial fluid." (PMID 33746606, 2021). "IL-6, TNF-α and LPS stimulate the expression of E2F2 in rheumatoid arthritis synovial fibroblasts via NF-κΒ, ERK and STAT3 pathway." (PMID 33530456, 2021). "Several pro-inflammatory mediators such as inducible cyclooxygenase enzyme (COX-2) and tumor necrosis factor-alpha (TNF—α) are usually observed in numerous inflammatory diseases, including inflammatory vascular diseases and rheumatoid arthritis." (PMID 34685875, 2021). "TNFα and IL6 are up-regulated in many inflammatory diseases, such as rheumatoid arthritis, inflammatory lung diseases and tumors." (PMID 34262459, 2021). "has also been associated with inflammatory disorders, such as rheumatoid arthritis and metabolic diseases, where it could play a role in sustaining inflammatory tone through the stimulation of TH17 and CD8+ T cells-derived pro-inflammatory cytokines (i.e., IFN-γ and TNF-α)." (PMID 34281224, 2021). "In adults with rheumatoid arthritis, psoriasis and IBD, correlations between concentration of TNF inhibitors and clinical response have been reported." (PMID 33926495, 2021). "TNF is a central cytokine in the pathogenesis of rheumatoid arthritis (RA)." (PMID 34588517, 2021). "In patients suffering from chronic inflammatory diseases such as rheumatoid arthritis (RA), proinflammatory cytokines such as TNF-alpha (TNF-α) are present in high concentrations in the circulation." (PMID 34367277, 2021). "TNF-α is reported to have a pivotal role in the pathogenesis of rheumatoid arthritis (RA)." (PMID 33530560, 2021). "There is also evidence that oxidative stress correlates significantly with specific inflammatory biomarkers such as Tumour Necrosis Factor Alpha (TNF-α) and C-Reactive Protein (CRP) in individuals with rheumatoid arthritis." (PMID 32878326, 2020). "In mouse models of rheumatoid arthritis and lupus, PR-957 treatment reduces cellular infiltration, autoantibody levels, and cytokine production, including IL-2, IL-6, IL-23, IFN-γ, and TNF-α, effectively alleviating the inflammatory response." (PMID 32595507, 2020). "TNF inhibitors (TNFi) are treatment options for patients with rheumatoid arthritis (RA)." (PMID 33124499, 2020). "Mangiferin downregulated TNF-α, IL-1β, and IFN-γ expression in TNF-α-stimulated CD3− synovial cells from rheumatoid arthritis (RA) patients, which indicated that mangiferin could be a potent candidate for the treatment of RA." (PMID 32019180, 2020). "As in chondrocytes, EGCG can also suppress the IL-1β-induced MMP-2 and TNF-α-induced MMP-1 and 3 production in rheumatoid arthritis synovial fibroblasts." (PMID 33374730, 2020). "For several inflammatory diseases, anti-TNF therapies are approved by the FDA and commonly used (e.g., rheumatoid arthritis or psoriasis)." (PMID 32521760, 2020). "Tumor necrosis factor (TNF) inhibitors are common therapies for certain autoimmune diseases, such as rheumatoid arthritis." (PMID 32421186, 2020). "Ozoralizumab, a bispecific therapy in active Phase-III clinical trials for rheumatoid arthritis, has a VH(TNFA)–VH(ALB)–VH(TNFA) configuration, where VH(TNFA) is a heavy chain designed to bind to TNF-α, and VH(ALB) is another heavy chain designed to bind ALB." (PMID 31555805, 2020).
rheumatoid arthritis (continued). "In most affluent countries during the past 20 years, treatment with biologic disease-modifying drugs (bDMARDs) such as TNF-alpha inhibitors has become part of the standard of care for patients with rheumatoid arthritis (RA), as well as for other types of inflammatory joint disease." (PMID 32600315, 2020). "In that study, PBMC samples from patients with rheumatoid arthritis had been stimulated with type I and type II IFN, while untreated samples and TNFα-stimulated samples were used as STAT1/2 pathway inactive controls." (PMID 33193365, 2020). "The three families of monoclonal antibodies approved to treat rheumatoid arthritis are directed against IL-6, B lymphocyte surface protein CD20 and TNFα, three targets of potential interest for further investigation in COVID-19 treatment." (PMID 33519443, 2020). "Anti-tumor necrosis factor (anti-TNF) biologics are established and effective treatments for a number of chronic inflammatory diseases including rheumatoid arthritis (RA), axial spondyloarthritis (axSpA), psoriatic arthritis (PsA), psoriasis (PSO), and Crohn’s disease (CD)." (PMID 33148261, 2020). "TNF‐α stimulation of synovial cells from rheumatoid arthritis patients induces expression of TSLP, and the blood concentration of TSLP in rheumatoid arthritis patients is elevated compared with the concentration in patients with an osteoarthritic knee." (PMID 32211586, 2020). "Several inflammatory cytokines, such as TNFα, IL-1, IL-6, IL-17, and receptor activator of nuclear factor-kappa B ligand (RANKL), play an important role in the pathogenesis of rheumatoid arthritis." (PMID 32079226, 2020). "Infliximab and Infliximab-abda to be used in this study are TNFα inhibitors currently FDA-approved for the treatment of autoimmune disorders, including Crohn’s disease and rheumatoid arthritis (ClinicalTrials.gov Identifier: NCT04425538)." (PMID 32882823, 2020). "IFN-γ together with TNF synergistically and significantly increased the cell surface levels of BAFF, Fn14, TACI, BAFF-R, BCMA, CD40L, ObR and IFN-γR in rheumatoid arthritis SF after 72 h incubation." (PMID 31964950, 2020). "Other mAbs target specific proteins involved in pathogenesis of disease, such as anti-TNFα mAbs infliximab and adalimumab that are used to treat inflammatory bowel disease (IBD) and rheumatoid arthritis (RA)." (PMID 33013848, 2020). "A recent retrospective study analyzed the influence of TNF-α inhibitors (TNFi) and an anti-IL-6 receptor antibody tocilizumab (TCZ) on glucose metabolism in 221 patients with rheumatoid arthritis, including 109 patients with T2D." (PMID 33233515, 2020). "It has been shown that the methotrexate treatment reduces the TNFα, IL1β, and IL6 production and increases the IL10 expression in the synovial tissue of rheumatoid arthritis patients." (PMID 31958219, 2020). "This urged the design of TNF-neutralizing agents, like the TNFR2-Fc Enbrel (/Etanercept) or TNF-neutralizing antibodies, that are now successfully used worldwide to limit Rheumatoid Arthritis (RA), psoriasis and Inflammatory Bowel Disease (IBD)." (PMID 32365592, 2020). "TQ was reported to downregulate pro-inflammatory genes such as IL-1, TNF-α, and toll-like receptors (TLR2, TLR4) and attenuate rheumatoid arthritis via the NFkB pathway." (PMID 32793594, 2020). "Anti-TNF therapies have been a major breakthrough in the management of rheumatoid arthritis (RA)." (PMID 32843099, 2020). "Based on these techniques, the first fully human therapeutic antibody, adalimumab (Humira), an anti-tumor necrosis factor α (TNFα) human antibody, was approved in 2002 by the US FDA for rheumatoid arthritis." (PMID 31894001, 2020). "We described that not only TNFα induced autophagy in peripheral blood mononuclear cells from rheumatoid arthritis (RA) patients, but also that the balance between autophagy and apoptosis was involved in response to therapy in RA patients treated with TNF inhibitors." (PMID 33424586, 2020).
rheumatoid arthritis (continued). "Additionally TNF is shown to be a major mediator of different inflammatory disease conditions like colitis and rheumatoid arthritis (RA)." (PMID 31488616, 2019). "Polyphenols reduce rheumatoid arthritis symptoms by regulating an extensive collection of RA-related molecules, including MAPK, IL-1β, IL-6, TNF-α, NF-κB, JNK, ERK1/2, AP-1 and COX-2." (PMID 31013659, 2019). "TNF-induced cell death was also mediated by TNFR127, and anti-TNF therapeutics are currently used to treat inflammatory diseases such as rheumatoid arthritis and Crohn’s disease." (PMID 31728004, 2019). "During rheumatoid arthritis (RA) treatment, long-term injection of antitumor necrosis factor α antibodies (anti-TNFα Abs) may induce on-target toxicities, including severe infections (tuberculosis [TB] or septic arthritis) and malignancy." (PMID 31194726, 2019). "Baricitinib is a JAK 1/2 inhibitor approved in the USA, EU, and Japan for rheumatoid arthritis, demonstrating potent inhibition of IL-6, D-dimer, CRP, TNF-α, IFN-α/β, and other pro-inflammatory cytokines." (PMID 31561750, 2019). "Biologics targeting tumor necrosis factor (TNF) are an effective therapy for reducing the inflammation and improving the signs and symptoms of rheumatoid arthritis (RA)." (PMID 31429794, 2019). "Monoclonal antibodies against TNF-α or TNF-α soluble receptors are among the most efficient biological DMARDs (disease-modifying antirheumatic drugs) available for the chronic treatment of rheumatoid arthritis (RA) and other chronic inflammatory diseases." (PMID 31080832, 2019). "Etanercept, a tumor necrosis factor inhibitor, has been used successfully for the treatment of multiple immune-mediated inflammatory diseases including moderate-to-severe rheumatoid arthritis (RA)." (PMID 31138316, 2019). "Complete disease remission is now achievable in people with psoriasis, rheumatoid arthritis (RA), and inflammatory bowel disease (IBD), where inhibition of the inflammatory cytokine tumor necrosis factor-α (TNF- α) remains the first-line biologic strategy." (PMID 30130616, 2019). "Ginkgetin reduced arthritic inflammation in rat adjuvant-induced arthritis, while resveratrol showed inhibitory effects on TNF-α-induced IL-1β and MMP-3 production in human rheumatoid arthritis fibroblast-like synoviocytes." (PMID 31757048, 2019). "However, TNF-α levels were found decreased, which may be explained by the concomitant treatment of rheumatoid arthritis with the immunosuppressant hydroxychloroquine and by previous mistreatment of leprosy with clofazimine, both known to interact with Th signaling." (PMID 31036692, 2019). "C5orf30 was also shown to inhibit the generation of cytokines involved in inflammation, such as TNF and IL1, and promote the expression of anti-inflammatory cytokines, such as IL10, in rheumatoid arthritis synovial fibroblasts." (PMID 30705370, 2019). "When transcriptional changes were mapped onto the Rheumatoid Arthritis KEGG pathway, excessive production of IL-1β and TNF by innate leucocytes was identified as a key change, corresponding with the changes observed in mice." (PMID 30552177, 2019). "TNF-α is a proinflammatory cytokine which mediated rheumatoid arthritis (RA) pathogenesis." (PMID 30713571, 2019). "Plenty of activated macrophages would assemble in RA joints, which could secrete some pro-inflammatory cytokines such as TNF-α and IL-1β which could accelerate the progression of rheumatoid arthritis." (PMID 30609724, 2019). "Interestingly, LAMR1 mRNA is downregulated in PBMC of patients with early rheumatoid arthritis (RA), and low gene expression is an independent predictor of poor response to anti-TNFα treatment, suggesting a role in RA pathogenesis." (PMID 30718719, 2019). "In rheumatoid arthritis synovial fibroblasts (RASF), PLD enzymes facilitate IL-17 and TNF-α induced expression of pro-inflammatory genes." (PMID 30555342, 2018).
rheumatoid arthritis (continued). "TNF‐α and IL‐1β promoted YY1 expression in the fibroblast‐like synoviocytes of rheumatoid arthritis patients." (PMID 29928577, 2018). "In our study, however, we recorded decreased CD55 expression after stimulating cultured HaCaT human keratinocytes with the cytokines TNF-α or IFN-γ, contrary to findings in other autoimmune diseases such as rheumatoid arthritis and SLE." (PMID 30473747, 2018). "miR-451 inhibits inflammatory cytokines secretion of TNF-α, IL-1β, and IL6 in human rheumatoid arthritis." (PMID 29652844, 2018). "In fact, TNF/TNFR system represents the single largest and validated therapeutic target in the clinics, accounting for major chronic autoimmune diseases, such as rheumatoid arthritis and psoriasis." (PMID 29743640, 2018). "Previously, TNFα was shown to downregulate Treg function since the TNFα-blocking agent Infliximab increased FOXP3 expression and restored their suppressive function in rheumatoid arthritis (RA) patients." (PMID 29619032, 2018). "Along with TNF-α, vascular endothelial growth factor-A (VEGF-A) protein is increased in the serum of rheumatoid arthritis patients." (PMID 29548992, 2018). "Therefore, CM reduced the production of TNFα, a cytokine with a central role in inflammation and tissue injury which has become an important target for the development of effective therapeutic agents in rheumatoid arthritis and other chronic inflammatory conditions." (PMID 29904354, 2018). "The successful inhibition of tumor necrosis factor-α (TNF-α) in rheumatoid arthritis (RA) and various other chronic inflammatory diseases like Crohn’s disease proved that the communication of various cytokines was disrupted due to blockade of TNF-α." (PMID 29848999, 2018). "Indeed, TNF inhibitors are already in clinically practice, since almost two decades and are powerful drugs in the therapy of Crohn’s disease, ulcerative colitis, psoriasis, and several arthritic diseases, including rheumatoid arthritis, psoriatic arthritis, and juvenile idiopathic arthritis." (PMID 29740434, 2018). "Psoriasis, PsA and rheumatoid arthritis are characterised by the secretion of several pro-inflammatory cytokines such as IL-2, IL-6, IL-8, IFN-γ and TNF-α." (PMID 29587639, 2018). "And upregulated genes were mainly enriched in TNF signaling pathway, osteoclast differentiation, MAPK signaling pathway, NF-kappa B signaling pathway, and rheumatoid arthritis." (PMID 30186872, 2018). "Clinical proof-of-concept of the extended half-life that is obtained in this way has been achieved for an anti-IL-6R and anti-TNF VHH fused to a serum albumin-binding VHH, used in the treatment of rheumatoid arthritis." (PMID 31544807, 2018). "Data from the British Society for Rheumatology Biologics Register shows that tumor necrosis factor inhibitor (TNFi) therapies are an effective treatment option for adults with JIA, with a safety profile similar to that seen in rheumatoid arthritis (RA)." (PMID 30305158, 2018). "Anti-TNF therapy, which limits TNFR signaling, has been tested in mouse models for different inflammatory diseases, such as rheumatoid arthritis, psoriasis, and bowel diseases." (PMID 29670621, 2018). "So far, five anti-TNF-α therapeutic agents are approved by both the Food and Drug Administration (FDA) and European Medicines Agency (EMA) for the treatment of rheumatoid arthritis." (PMID 29881431, 2018). "As CCR6 is expressed on many cell types that drive the inflammatory process in rheumatoid arthritis (RA), we also addressed the role of CCR6 in an additional arthritis model, the human TNF transgenic mouse model." (PMID 30133119, 2018). "The discovery of the role of tumor necrosis factor (TNF) in the pathogenesis of rheumatoid arthritis (RA) has led to anti-TNF biological therapy as a breakthrough in the treatment of chronic autoimmune diseases, such as RA, Crohn’s disease, psoriatic arthritis, and spondyloarthritis." (PMID 30314507, 2018).